BRAF (B-Raf proto-oncogene, serine/threonine kinase)
Diseases named in the same sentence as BRAF in open-access papers (continued):
Sharing a sentence is not in itself a finding about the gene and the disease.
melanoma (continued). "One study comparing NAM (n = 54) and non-NAM acral melanoma (n = 78) revealed that, among common melanoma driver genes, mutations in KIT and KRAS were predominantly found in NAM, whereas those in BRAF and NRAS occurred almost exclusively in acral melanoma." (PMID 36983205, 2023). "The identification of driver mutations, such as BRAFv600E/K, along this pathway has led to the development of targeted therapy with dual BRAF and MEK inhibition, which has contributed to the remarkable improvement in overall survival of patients with BRAFV600 advanced melanoma." (PMID 37370834, 2023). "A novel BRAF splicing isoform lacking exons 2-10 was detected in one out of five patients with D/T combination resistant melanoma tumors and that was undetectable in the pre-treatment tumor." (PMID 37834284, 2023). "Studies have shown that vemurafenib does not have activity in wild-type BRAF melanoma cells, unlike other drugs such as sorafenib, which can block both wild-type and mutated BRAF." (PMID 37446932, 2023). "Moreover, MALAT1 expression also was significantly decreased in melanoma compared to healthy skin when put in relationship to gene expression of the MAPK pathway genes NRAS, BRAF, MEK1, MEK2, ERK1, and ERK2." (PMID 37235843, 2023). "PTEN-negative or AKT3-overexpressing melanomas do not undergo apoptosis in response to BRAF inhibition." (PMID 37762707, 2023). "BRAF mutations are the primary drivers of melanoma in younger patients, while in older patients, neither NRAS nor BRAF was mutated in nearly half of the patients who were tested, suggesting a polygenic or lesser-known genetic driver." (PMID 36909026, 2023). "Unlike the high efficacy of BRAF targeting strategies observed in melanoma, monotherapy with V600E-specific kinase inhibitors (vemurafenib, dabrafenib) has been proven to be ineffective in metastatic colorectal cancer (mCRC)." (PMID 37240418, 2023). "Regarding the melanoma, most patients were BRAF-negative (N = 10, 66.7%), with the most common initial stages being T4 (N = 6, 40%) and N1 (N = 7, 46.7%)." (PMID 37297014, 2023). "We next chose chemotherapeutic medicines, BRAF/MEK inhibitors (Dabrafenib, Trametinib) and immunotherapy drugs (pembrolizumab, nivolumab, ipilimumab) that are already used to treat melanoma to assess the sensitivities of individuals in the low- and high-risk categories to these medications." (PMID 36824136, 2023). "In this case, anti-BRAF melanoma immunotherapy has shown its usefulness in a small but no less important percentage of patients with NSCLC." (PMID 36836402, 2023). "The application of BRAF inhibitors, first as monotherapy and subsequently also in combination with MEK inhibitors, significantly improved response rates and prolonged progression-free and overall survival of patients with BRAFMut melanomas." (PMID 37464364, 2023). "Resistance to inhibitors of BRAF (BRAFi) and MEK (MEKi) is linked to non-mutational adaptation of melanoma cells during the early response and the following drug-tolerant phase of treatment." (PMID 37563469, 2023). "In another study, a mouse model of melanoma showed that inhibiting FATP2, another critical lipid metabolism transporter, in PMN-MDSCs using lipofermata, led to enhanced tumor regression when combined with BRAF/MEK inhibitor." (PMID 37700339, 2023). "Further studies are needed to better define the patients with non-V600-mutated melanoma who would derive meaningful clinical benefit from MEK inhibitors with and without BRAF inhibition." (PMID 37370834, 2023). "Besides the demonstration of the capability of LNP-miRs in combination with MAPKi to delay or impair the emergence of de novo drug resistance, another challenging field of study is the overcoming of acquired resistance to BRAF and MEK inhibitors in melanoma." (PMID 36418472, 2023).
melanoma (continued). "A recent study demonstrated that ubiquitin-specific peptidase 22 (USP22) interacted with and stabilized YAP, which in turn conferred resistance to the BRAF inhibitor vemurafenib and provided new therapeutic avenues to target USP22/YAP as an option for melanoma treatment." (PMID 36694209, 2023). "The tissues of 68 melanoma patients were analyzed and BRAFV600E mutation was present in 39.7%, the BRAFV600K mutation in 7.4%, and negative (wild-type) for BRAF in 52.9%." (PMID 36765875, 2023). "Since a cancer-promoting role of BMP signaling has been reported in a BRAFV600E-initiated melanoma model of zebrafish, differential biological effects of RAS and BRAF oncogenic signaling in the regulation of key pathways and genes should be taken into consideration." (PMID 38020918, 2023). "In our cohort, adjuvant immunotherapy was applied in 54 (37%) melanoma BRAF-positive and 93 (63%) BRAF-negative patients." (PMID 37686659, 2023). "For example, dual BRAF/MEK inhibition induces cleavage of pyroptosis marker gasdermin E (GSDME) and intra-tumoral T cell infiltration, but BRAFi/MEKi resistance attenuates these responses in melanoma." (PMID 37834284, 2023). "Although the reasons why BRAF‐mutant melanoma responds better to combination ICIs remain unclear, differences in the tumor microenvironment (TME) between BRAF‐mutant and wild‐type melanoma are indicated." (PMID 37584204, 2023). "No cytotoxic effect was observed for the primary melanoma cell line WM3211 (VGP), with a wild type for BRAF, PTEN, N-RAS, and CDK4, and mutation at position 576 in the c-KIT gene, even for long incubation times—72 h." (PMID 37097377, 2023). "It confirms that RIPK4 does not affect the PEBP1/RIPK4 axis or the BRAF/MEK/ERK pathway in melanoma." (PMID 36765875, 2023). "On the other hand, G-361 is a BRAF/V600E and TERT mutant amelanocytic melanoma cell line." (PMID 38069171, 2023). "In the metastatic BRAF V600 mutant melanoma, the BRAF ctDNA negative-patients at baseline therapy had a high RR to target therapy, while the BRAF-positive patients had a shorter PFS and OS." (PMID 36937316, 2023). "Although downregulation and upregulation of RIPK4 does not affect signal transduction through the BRAF/MEK/ERK pathway in melanoma, it can inhibit cell proliferation and the FAK/AKT pathway." (PMID 36765875, 2023). "Although immunotherapy and targeted therapy for BRAF have significantly improved the overall survival and quality of life of patients with advanced melanoma, some patients still do not respond to them." (PMID 37959729, 2023). "For instance, genomic analyses have established the molecular classification of melanoma based on the most frequent driver oncogenes (BRAF, NRAS, KIT) and have also revealed a long list of rare events, whose contribution to melanoma progression toward metastasis remain mostly unclear." (PMID 37047539, 2023). "In summary, RIPK4 kinase does not directly affect signal transduction through the BRAF/MEK/ERK pathway in melanoma." (PMID 36765875, 2023). "We found no statistical difference in survival between patients with BRAF wild‐type and BRAF mutant melanoma." (PMID 38083908, 2023). "This suggested that M. cochinchinensis seed extracts contains multiple anticancer compounds that have a synergistic effect on melanoma cells irrespective of their BRAF status." (PMID 36678596, 2023). "In vitro data also suggests a possible synergistic effect of sequencing temozolomide after vemurafenib in BRAF-mutant melanoma cells, without cross-resistance." (PMID 36988735, 2023). "Finally, two groups have demonstrated that hyperactivation of ERK signaling is responsible for cell death upon drug withdrawal in BRAF and MEK inhibitor-addicted melanoma cells." (PMID 37803324, 2023). "Although MAPKi is generally an effective strategy in BRAF mutant melanoma, it is of no clinical benefit in a BRAF WT background." (PMID 37072838, 2023).
melanoma (continued). "Patients with BRAF mutant melanomas treated with bevacizumab no longer exhibited significantly improved disease-free survival (HR 0.81 95% CI 0.60–1.10) nor overall survival (HR 0.80; 95% CI 0.57–1.13, p = 0.21) rates." (PMID 36539575, 2023). "Adjuvant anti‐PD‐1 monotherapy identified no disease‐free survival benefit in BRAF mutant melanoma than IFN/OBS in our study." (PMID 37403699, 2023). "A multi-centric study of BRAF inhibitor-resistant melanoma tissue samples, analyzed after disease progression, most detected secondary genomic alterations in the MAPK/ERK signaling pathway, BRAF copy number gains and BRAF alternative splicing, as mechanistic drivers of resistance." (PMID 37920169, 2023). "Here we used whole genome sequencing to genetically characterize the triple-wild-type melanoma (TWM), termed here as BRAF, RAS and KIT wild type (the most frequent oncogenic drivers of skin melanoma), using the most common histological forms and excluding rare ones." (PMID 36980598, 2023). "The combination of nivolumab and ipilimumab leads to the best outcome, and the Food and Drug Administration (FDA) approved this cocktail as the best treatment for both advanced BRAF-negative melanoma patients and for melanoma patients with BRAF mutation." (PMID 36831417, 2023). "Current therapeutic options in advanced melanoma include PD-1 inhibitors associated or not with CTLA-4 or lymphocyte-activating gene (LAG)-3 inhibitors and in cases of BRAF V600E/K mutated BRAF inhibitors, called targeted therapy." (PMID 37569757, 2023). "The BAMM trial (BRAF Autophagy and MEK Inhibition in Melanoma), which combined Dabrafenib, Trametinib, and HCQ, demonstrated these combinations are effective and safe in patients with BRAFV600-mutant melanoma." (PMID 38105263, 2023). "In the adjuvant setting, BRAF and MEK inhibitors combination has been approved for BRAFV600‐mut patients with Stage III disease, while anti‐PD1 monotherapy approved for both mutant and wild‐type melanoma." (PMID 37403699, 2023). "In addition, combinations of MS934 with either BRAF or PI3K inhibitors provided a potent antiproliferative response in CRC and melanoma cells." (PMID 37892237, 2023). "In addition, BRAF and MEK inhibitor combination therapy provided promising clinical results against melanoma brain metastases which have prompted assessing baseline clinical features associated with outcomes." (PMID 37920169, 2023). "The rationale was that resistance to the MEK inhibitor by reactivating the pathway could be blunted by also blocking downstream with the CDK4/6 inhibitor, similar to combined BRAF and MEK inhibition in melanoma." (PMID 37126527, 2023). "BRAF mutations are more likely to be detected in SSM, while NM is associated more strongly with the ‘non-nevus’ melanoma pathway development model and NRAS mutations." (PMID 37374151, 2023). "We then measured the TCF12 protein stability in melanoma cells with or without BRAF inhibition and found that suppression of the BRAF pathway greatly reduced TCF12 protein stability." (PMID 37760480, 2023). "However, when the three major drivers, BRAF, RAS and KIT, are wild type, the remaining tumors, called here triple-wild-type melanomas (TWMs), are genetically very heterogenous and very different from the rare histological ones." (PMID 36980598, 2023). "Moreover, we assessed the association of TILs in metastatic tissue and survival outcomes, including progression-free survival (PFS) and melanoma-specific survival (MSS) after first-line anti-PD-1-based therapy and targeted therapy with BRAF and MEK inhibitors." (PMID 37295047, 2023). "We also discuss how targeting BRAF-mutant dedifferentiated cells and ECM-based mechanotransduction pathways may overcome melanoma cross-resistance." (PMID 36774337, 2023).
melanoma (continued). "The level of miR-216b in MeWo melanoma cells carrying the wild-type BRAF gene was not significantly altered by vemurafenib, suggesting an association between miR-216b downregulation upon vemurafenib treatment and BRAF mutations." (PMID 37834222, 2023). "In the “Other tumors group” four rearrangements involving BRAF gene were detected (three melanoma: BRAF::CNNM2, BRAF::ERC1, BRAF::MAD1L1 and one pancreatic adenocarcinoma BRAF::SND1), but also one ETV6::NTRK3 (colorectal cancer) and one FGFR3::TACC3 (urothelial cancer)." (PMID 37708140, 2023). "The authors report that BRAF/VEGFA targeting reverses immune cell exclusion by increasing the infiltration of CD8 T cells and M1–macrophages, allowing remodeling of the tumor microenvironment and sensitizing melanoma cells to immune checkpoint blockade." (PMID 37183363, 2023). "TTs include BRAF inhibitors (BRAFi) and MEK inhibitors (MEKi) which inhibit the commonly over‐activated mitogen‐activated protein kinase (MAPK) pathway, responsible for cell proliferation and survival in melanoma." (PMID 36967556, 2023). "As a small-molecule HSP90 inhibitor, AT13387 has long sustained antitumor activity in melanoma, and combination of AT13387 with BRAF/MEK inhibition could delay the emergence of drug resistance." (PMID 37950289, 2023). "BRAF inhibition with or without MEK inhibition has since been shown to have activity against cancers other than melanoma, with the exception of colorectal cancer." (PMID 36801912, 2023). "PHBs have an essential role in the RAS-driven activation of the MAPK/ERK1/2 pathway via CRAF, the key mediator in wild-type BRAF melanoma where there are no effective therapies." (PMID 37508519, 2023). "The non-overlapping mutations in BRAF, NRAS, and NF1 are sometimes referred to as “driver” mutations, due to their ability to independently promote growth, proliferation, and survival of melanoma cells." (PMID 37444637, 2023). "BRAF (serine/threonine kinase), which is a member of the Raf family, plays a critical role in MAPK pathway signaling, with a substitution from valine to glutamic acid at codon 600 (V600E) in ~50% of melanomas." (PMID 36844227, 2023). "Accordingly, we hypothesized that co-targeting DNA repair (PARP-1) and relevant activated RTKs, c-Met in particular, may radiosensitize wild-type B-Raf Proto-Oncogene, Serine/Threonine Kinase (WTBRAF) melanomas where RTKs are often upregulated." (PMID 37215708, 2023). "Unlike melanoma, BRAF inhibitors alone have shown poor clinical benefit in patients with BRAF mutant colorectal cancer." (PMID 37302081, 2023). "All 10 cases tested (100%) were negative for BRAF V600E alterations, which are common in other types of melanoma." (PMID 36416305, 2023). "First, we confirmed that the RIPK4 structure and sequence of RIPK4 is similar to both the BRAF protein and its mutant form and then verified that the BRAFV600 E or K mutation does not affect the expression of the RIPK4 protein in melanoma specimens." (PMID 36765875, 2023). "For instance, p38 plays a tumor suppressive role in NRAS-mutant melanoma but not in BRAF-mutant melanoma, even though BRAF and NRAS are part of the same MAPK pathway." (PMID 36765834, 2023). "Previous studies have shown that dabrafenib or vemurafenib, a selective BRAF inhibitor, significantly improves progression-free survival (PFS), clinical response rate (RR), and overall survival (OS) compared to chemotherapy in BRAF-mutant melanoma patients." (PMID 37205993, 2023). "Similarly, perillyl alcohol overcomes resistance to BRAF and MEK inhibitors in melanoma cells by inducing apoptosis and inhibiting the MAPK signaling pathway." (PMID 37515699, 2023). "Another study proposed a negative feedback mechanism in BRAF-mutant melanoma cells to limit ROS production." (PMID 38139812, 2023).
melanoma (continued). "Although sequential therapy, that is, treatment with a BRAF inhibitor followed by BRAF/MEK dual inhibition is not recommended in the management of BRAF-mutant melanoma, we decided to add the MEK inhibitor cobimetinib to vemurafenib." (PMID 36967525, 2023). "First, we tested whether the BRAF status affects VEGF secretion by quantifying intracellular and secreted VEGF through ELISA in a panel of BRAFV600E and BRAFWT melanoma cell lines." (PMID 36539575, 2023). "We found that pronounced induction of AR expression occurred in a panel of primary and established melanoma cells already by 48 hours of treatment with DAB and other BRAF and MEK inhibitors, while inhibitors of other key signaling pathways, such as NF-κB, STAT3, and AP-1 exerted no such effect." (PMID 37838724, 2023). "Initially, we crossed mice with BRAF-driven murine melanoma previously developed in our lab with mice lacking different AKT isoforms and monitored the mice derived from these crosses for melanoma development." (PMID 37894325, 2023). "The presence of these differential factors leads to adaptive resistance in thyroid cancer at the early stage of treatment with BRAF inhibitors, unlike melanoma, which develops adaptive resistance to BRAF inhibitors at a later stage." (PMID 37325052, 2023). "In the literature, the triple-wild-type melanoma (TWM) refers to those where BRAF, NRAS and NF1 are not mutant." (PMID 36980598, 2023). "To determine if stable MALAT1 RNA levels are a common requirement in melanoma, we applied MALAT1-ASO treatment to a group of NRAS- and BRAF-mutant melanoma cell lines in vitro, including primary derived cell lines and cell lines with acquired resistance to the MEKi trametinib." (PMID 37235843, 2023). "As a consequence, it exerts a negative impact on MAPK pathway, and sensitizes melanoma cells to BRAF and MEK inhibitors, both in vitro and in vivo." (PMID 37013641, 2023). "BRAF inhibitors (BRAFi), like vemurafenib, suppress Nrf2 expression in BRAF mutant melanoma cells, although the effect is not significant, suggesting that other oncogenes also trigger the Nrf2 signaling pathway." (PMID 36747120, 2023). "Increased sPD-L1 levels were observed after radiotherapy in contrast to no significant change after anti-BRAF therapy in melanoma." (PMID 36639643, 2023). "In melanoma and other types of cancer, activating mutations in NRAS and BRAF can constitutively auto-activate the kinases without the requirement of ligand mediated activation, causing hyperactivation of the pathway." (PMID 37235843, 2023). "While TT is only effective for BRAF‐mutated melanoma, previous studies have demonstrated that COMBI‐ICI is more effective for unresectable melanoma than TT and single‐agent ICI, regardless of BRAFV600 mutational status." (PMID 38083908, 2023). "Data from population-based real-world cohorts, such as the Dutch Melanoma Treatment Registry (DMTR)., could be used to directly compare the effectiveness of adjuvant BRAF/MEK-inhibition to that of adjuvant anti-PD-1 treatment in daily practice." (PMID 36672358, 2023). "Our group, recently showed that the simultaneous BRAF/VEGFA targeting, induced the tumor infiltration of M1 macrophages, with a mandatory role in determining the delay of acquired resistance to BRAFi in a A375 melanoma model." (PMID 37183363, 2023). "The patient with BRAF (#56) V600+ mutant melanoma who carried both CDKN2A and MITF germline PVs did not respond to adjuvant therapy with TT nor to first-line treatment with ICI." (PMID 36901733, 2023). "Besides BRAF/MEK inhibitors, other drugs including alkylating agents are used in clinics in the treatment of melanoma patients." (PMID 36674479, 2023). "Finally, two lncRNAs regulated by the BRAF pathway-MIR31HG and RMEL3- promoted melanoma proliferation and in vivo tumor growth in preclinical models by preventing p16INK4A-dependent cellular senescence and stimulating MAPK and PI3K pathways, respectively." (PMID 35159386, 2022).